IL6 (interleukin 6)
Diseases named in the same sentence as IL6 in open-access papers (continued):
Sharing a sentence is not in itself a finding about the gene and the disease.
Obesity (continued). "The pro-inflammatory cytokines TNF-α and IL-6 stimulate PAI-1 expression in human AT and adipocytes via NF-κB activation, suggesting a close relationship between PAI-1 and obesity-induced inflammation." (PMID 35909571, 2022). "In this study, cooked adzuki bean significantly inhibited body weight gain, reduced serum TG and proinflammatory cytokines (IL-6, TNF-α, and LPS) levels, and alleviated obesity-related hepatic steatosis and liver injury." (PMID 35782919, 2022). "The therapeutic effect of adipose-derived MSCs on obesity-related complications (e.g., NAFLD, CVD, and renal diseases) in animal models of diet-induced obesity derives from the attenuation of inflammatory cytokines such as TNF-α and IL-6." (PMID 35895169, 2022). "In obesity, increased production and secretion of a wide range of inflammatory molecules, including tumor necrosis factor (TNF)-α and interleukin-6 (IL-6) was reported in white adipose tissue." (PMID 36452324, 2022). "Previous studies reported that DPP4 inhibitors could ameliorate high-fat diet-mediated obesity-related glomerulopathy, which may relate to the improved insulin sensitivity and reduced local inflammation through inhibiting macrophage infiltration and IL-6 and TNF-α secretion." (PMID 35935760, 2022). "Obesity correlates with the severity of inflammation, which is controlled mostly by CD4+ T lymphocytes; therefore, there is an increase in IL-6 secretion, which makes CD4+ cells differentiate to Th17." (PMID 36364955, 2022). "Interestingly, obesity is characterized by excess fat accumulation in white adipose tissue, in which inflammation is activated through the secretion of pro-inflammatory factors such as IL-6, IL-12, and TNFα, and transcription is activated via the NF-κB activation pathway." (PMID 35326476, 2022). "The expansion of adipose tissue in obesity leads to increased macrophage infiltration and inflammation with an increased production of proinflammatory cytokines such as TNF-a and IL-6." (PMID 36547041, 2022). "Another aspect of obesity and T2DM is the increase in the serum levels of inflammatory cytokines such as interleukin-6 (IL-6) and tumor necrosis factor-alpha (TNF-α)." (PMID 36355818, 2022). "Other nominally significant associations were established between WHOCS scales and: IFNL4 rs12979860, ACEIs, obesity, ARA-II, HCP5 rs2395029, ACE rs1799752, DPP4 rs17574, HMOX1 rs2071746, IL10 rs1800896, IL6 rs1818879, NFKB1 rs28362491, and MX1 rs469390." (PMID 35636966, 2022). "Elevated concentrations of some inflammatory cytokines are seen in obesity, such as interleukin 4 (IL-4), monocyte chemoattractant protein 1 (MCP-1), IL-6, and TNF-α." (PMID 36295052, 2022). "After activation of macrophages, levels of TNF-α, IL-6, and RANTES elevated during obesity maintain homeostatic control of AT mass." (PMID 35456006, 2022). "SAA is a nonspecific acute phase protein mainly produced by the cytokines IL-1β, IL-6, and TNF-α in liver cells, which increase in chronic inflammatory processes, as in diabetes and obesity." (PMID 35047039, 2022). "Of note, interleukin-6 (IL-6), interleukin-8 (IL-8), and monocyte chemo-attractant protein 1 (MCP-1) were the major adipokines secreted by the CAAT IBC patients with obesity." (PMID 35927653, 2022). "In cases of obesity, the adipocytes secrete pro-inflammatory cytokines such as TNF-α and IL-6, which stimulate the liver’s production of CRP, altering the hosts’ immune response, and increasing their susceptibility to bacterial infections." (PMID 36661547, 2022). "Inflammatory cytokines in adipose tissue induced by obesity, such as TNF-α, IL-1β, and IL-6, increased." (PMID 35883829, 2022). "Interleukin-6 and TNF-α are both critical mediators of inflammation, with increased levels in obesity." (PMID 36258233, 2022).
Obesity (continued). "Reportedly, 25 μM 6-gingerol inhibits lipid accumulation and obesity-induced inflammatory responses by inhibiting the production of the inflammatory mediators MCP-1 and IL-6 in co-culture conditions with 3T3-L1 and RAW264.7 cells." (PMID 35807667, 2022). "In the BC subnetwork, the targets with the top three BC values were albumin (ALB), interleukin-6 (IL6), and AKT serine/threonine kinase 1 (AKT1), which were considered the core targets connected with microbes to alleviate obesity." (PMID 36139478, 2022). "By the correlation analysis, we identified 35 key genera, which were significantly correlated with features of obesity (body weight gain), dyslipidemia (TC, TG, HDL‐C, and LDL‐C), proinflammatory cytokines (serum IL‐6, IL‐1β, and TNF‐α), and LPS." (PMID 36348812, 2022). "In support of this fact, some studies demonstrated that there is an overexpression of IL-6 and TNF-α deriving from macrophages residing in adipose tissue in individuals with obesity and overweight compared with normal weight adults." (PMID 35682490, 2022). "Mostly in freshly isolated PBMC from individuals with obesity which showed significantly higher expression levels of pro-inflammatory cytokines (IL-1β, MCP-1, IL-8, and IL-6) as compared to control subjects." (PMID 35896710, 2022). "Elevated Il-6 levels in the lateral parabrachial nucleus (LPBN) decrease food intake and intensify thermogenesis in IBAT, which suggests that myokines act as obesity regulators in the brain." (PMID 36364955, 2022). "Previous studies show positive correlations between Leptin, Visfatin, Resistin and Adipsin and circulating inflammatory markers such as IL-6 and CRP in individuals suffering from obesity." (PMID 35684160, 2022). "Furthermore, obesity promotes the initiation of numerous pro-inflammatory pathways by causing TLR4-mediated inflammatory responses that involve activation of the transcription factor NF-κB and the production of pro-inflammatory mediators such as IL-6, IL-1, and TNF-α." (PMID 35740977, 2022). "The mechanisms whereby obesity leads to increased CRP levels are not clearly understood, but inflammatory cytokines such as IL-6 are produced by adipose tissue, and this process is exacerbated in conditions of increased central adiposity." (PMID 35035976, 2022). "Some of the common features between the sexes of obesity-induced CRC include increased levels of leptin, IL-6, insulin, and C-reactive proteins (CRP-1), and decreased adiponectin levels." (PMID 36429114, 2022). "CGA has been shown to reduce oxidative damage, control the inflammatory response through inhibition of TNF-α, IL-6, and IL-1β, increase insulin sensitivity, and prevent CVD and obesity through lipid metabolism modulation." (PMID 35683374, 2022). "There is a chronic low-grade inflammation developing in obesity, mediated by inflammatory cytokines such as tumor necrosis factor-alpha (TNF-α), interleukin 6 (IL-6), monocyte chemoattractant protein-1 (MCP-1), and interleukin 8 (IL-8)." (PMID 36003642, 2022). "Further elevated circulating maternal IL-6 and CRP levels have been reported in pregnant women with obesity." (PMID 35348641, 2022). "An increase in M1 macrophages, which form a structure around adipocytes and release pro-inflammatory mediators such as IL-1, IL-6, IL-12, TNF-α, and chemokines, is part of the alteration in immune cell profile that is characteristic of obesity." (PMID 35740977, 2022). "The level of IL-10 in the obesity group was much lower than that in the control group, while the levels of TNF-α, IL-6, and LPS showed a significant upward trend." (PMID 35600958, 2022). "Activated C-Jun transcription factors bind to AP-1 sites, thereby promoting the expression of pro-inflammatory factors (e.g., TNFα, IL1β, IL6, etc.), which play a key role in impaired glucose tolerance and insulin resistance by HFD-induced obesity." (PMID 35715850, 2022).
Obesity (continued). "Obesity inhibits the secretion of the anti-inflammatory adiponectin and increases the secretion of adipokines and pro-inflammatory proteins (TNF-α, IL-6, IFNγ, and TGF-β1), which enhance overexpression of MHC-II in the primary adipocytes." (PMID 35205204, 2022). "This is in contrast to what is typically seen in individuals with obesity, who tend to have higher circulating TNF‐α and IL‐6 that subsequently decrease following interventions that combine diet and exercise that lead to reductions in fat mass." (PMID 35312183, 2022). "Apparently, inflammatory cytokines are able to induce IR in both adipose tissue and muscle.in case of obesity, adipocytes produce plenty of cytokines such as TNF-α and IL-6, the primary stimulator of the production of CRP in the liver." (PMID 35318405, 2022). "Metabolically unhealthy obesity leads to the overexpression of CRP and IL-6, resulting in low-grade chronic inflammation." (PMID 34991564, 2022). "We found that plasma IL-1β, IL-6, IL-8, IL-12, IL-17, IL-21, IL-32, and TNF-α levels were elevated in obese children with NAFLD compared to subjects with simple obesity." (PMID 36530698, 2022). "We demonstrate here that maternal obesity leads to early-onset obesity with WAT overactivity and elevated serum IL-6 and leptin concentrations in the offspring." (PMID 35896539, 2022). "Circulating IL-6 levels are shown to positively correlate with CRP levels and CRP was shown to be elevated in obesity and IBD." (PMID 35276983, 2022). "Various local or systemic cytokines are increased in obesity, including IL-1α, TNF-α, leptin, and IL-6, while IL-1α, in combination with TNF-α and IL-6, is involved in the pathology of atherosclerosis in obese individuals." (PMID 36311488, 2022). "Obesity is a chronic pro-inflammatory state, with increased circulating levels of the inflammatory markers C-reactive protein (CRP), interleukin-6 (IL-6) and tumour necrosis factor-alpha (TNF-α)." (PMID 34857870, 2022). "Specifically, we observed the levels of IL-1β, IL-6, IL-8, IL-12, IL-17, IL-21, IL-32, and TNF-α were significantly higher in the NAFLD group than in the simple obesity group (all P < 0.001)." (PMID 36530698, 2022). "Secretion of TNFα, IL-6, and MCP-1 from both myocytes and skeletal muscle are increased in chronic conditions such as obesity and have been shown to contribute to impaired glucose uptake and insulin resistance." (PMID 35889783, 2022). "Elevated plasma levels of C-reactive protein (CRP) and pro-inflammatory cytokines such as IL-6, TNF-α, MCP-1, IL-8, and IL-7 confirmed the existence of an inflammatory state in individuals with obesity." (PMID 35896710, 2022). "Obesity activates the NF-κB pathway and increases the expressions of proinflammatory cytokines such as TNF-α and interleukin-6 (IL-6) in adipose tissue, thereby disrupting insulin signaling and triggering insulin resistance and NAFLD." (PMID 36305727, 2022). "CAP modulated the fasting blood glucose and insulin concentrations as well as decreased the levels of proinflammatory cytokines interleukin-1β and interleukin-6 to treat high-fat, or high-sucrose (HFHS) diet-induced obesity." (PMID 36263142, 2022). "Studies have demonstrated that subjects with obesity have elevated circulating pro-inflammatory cytokines, including tumor necrosis factor-α (TNF-α), interleukin-6 (IL-6) and C-reactive protein (CRP)." (PMID 35252310, 2022). "ω3-Polyunsaturated fatty acids exert anti-inflammatory effects and can reduce the levels of inflammatory cytokines, such as IL-1, IL-6, and TNF-α, and mitigate adipose tissue inflammation in animal models of obesity." (PMID 35887932, 2022). "The results of this meta-analysis showed that aerobic training (AT) and aerobic plus resistance training (AT + RT) reduced the levels of IL-6 and CRP in adolescents with obesity." (PMID 36293806, 2022).
Obesity (continued). "Compared with the control group, the level of anti-inflammatory factor IL-10 in the cord blood was decreased in the obesity group, while the levels of proinflammatory factors TNF-α, IL-6, and LPS were increased." (PMID 35600958, 2022). "All treatments equally prevented the obesity-induced increase in the adipocyte area (p < 0.05) and in the mRNA levels of MCP-1 (p < 0.001 for all) and IL-6 (p < 0.01 for all) in retroperitoneal adipose tissue." (PMID 36139877, 2022). "Higher bronchial alveolar lavage fluid cell count with an increased neutrophil percentage and elevated concentration of IL-6 was also observed in the same study suggesting that an activated pro-inflammatory state may play a role in reactive airway disease in children born to mothers with obesity." (PMID 36189369, 2022). "Previous study demonstrated that 10% (v/v) plasma from diet-induced obesity (DIO) mice induced higher expression of both CCL2 and IL-6 mRNA than plasma from lean mice in SVFs from DIO mice, but did not have this effect on SVFs from lean mice." (PMID 35883204, 2022). "Obesity-induced hyperleptinemia stimulates the production of pro-inflammatory cytokines such as TNF-α, IL-6, IL-2, IL-1β, and interferon-γ (IFN-γ) by monocytes and T-helper 1, and also inhibits the production of the anti-inflammatory cytokine IL-4." (PMID 36499312, 2022). "Obesity usually leads to IR, Some studies have shown that altered secretion of cytokines in obesity such as TNF-α, IL-6, and leptin induce IR in obesity, while adiponectin stimulates insulin sensitivity." (PMID 36451420, 2022). "IL-6 is a very promising therapeutic target for obesity, and acupuncture is likely to modulate inflammation and thus affect obesity through the TLR4/NF-κB/IL-6 signaling pathway." (PMID 36105933, 2022). "It has been shown that serum levels of IL-6 and TNF-α are correlated with body mass index (BMI) and obesity." (PMID 36355818, 2022). "This analysis highlighted an increase in pro-inflammatory cytokines TNF-α and IL-6 and upregulation of NF-κB-related genes NFKB1 and RELA in obesity." (PMID 35215414, 2022). "Purified sweet cherry anthocyanins at 200 mg/kg in mice reduced body weight by approximately 11.2% and decreased the expression of the IL-6 and TNF-α genes in white adipose tissue (WAT), slowing down the progression of obesity in these mice." (PMID 35740977, 2022). "Adipose cells secrete approximately 50 exclusive cytokines, chemokines, and hormonal elements including IL-6, IL-8, IL-1β, tumor necrosis factor (TNF)-α, VEGF, CCL2, CCL5, and MMP9, which can also make a contribution to obesity and TME." (PMID 35205204, 2022). "The data obtained in the different studies show a significant increase in IL-6 and CRP values in the PD and obesity groups compared to the control groups, finding a positive correlation with PD and obesity." (PMID 36547041, 2022). "Thus, adipose IL-6 might be a potential target for correcting obesity-related complications." (PMID 36276810, 2022). "When the number of pro-inflammatory M1 ATMs is increased in obesity, TNF-α and IL-6 are highly secreted, which are involved in the insulin resistance of adipocytes by inhibiting insulin signaling and stimulating lipolysis of adipocytes." (PMID 36499655, 2022). "A controlled clinical trial evaluated the anti-inflammatory and antioxidative effects of OEA (250 mg/day) on obesity, as well as assessing LPO, TAC, CRP, IL-6, and TNF-α levels." (PMID 36120593, 2022). "The results showed that CIP decreased the serum levels of inflammatory cytokine TNF-α and the mRNA expression levels of IL-6, IL-1β, and TNF-α in mice, suggesting that CIP improved inflammation during the development of obesity." (PMID 36235584, 2022). "With the increase of various inflammatory factors in serum, such as C-reactive protein (CRP), IL-6, and tumor necrosis factor-α (TNF-α), obesity is essentially a chronic low-grade inflammatory state that is difficult to eliminate." (PMID 36105933, 2022).
Obesity (continued). "Among them, AT + RT was more effective than other training modalities in reducing IL-6 and CRP in adolescents with obesity." (PMID 36293806, 2022). "This is evidenced by several clinical studies showing that serum OCN level was negatively correlated with systemic inflammatory markers, such as interleukin-6 (IL-6) and C-reactive protein (CRP), in patients with diabetes, obesity, or metabolic syndrome." (PMID 35625743, 2022). "Obesity can induce gastritis mediated by tumor necrosis factor-α (TNF-α), interleukin-6 (IL-6), and chemoattractive protein-1 (MCP-1)." (PMID 35954495, 2022). "Numerous studies have reported that certain genes affect the progression of obesity, including peroxisome proliferator-activated receptor γ (PPARG), CCAAT enhancer binding protein α (C/EBPα), and interleukin 6 (IL6)." (PMID 35328013, 2022). "Recent studies also show that TNF-α, IL-6, and IL-1 promote IR, with TNF-α level as the main link between obesity and IR." (PMID 35956404, 2022). "Topological analysis and modular analysis revealed the role of HJJPD in the treatment of simple obesity by acting on SOCS-3, JAK2, LepRB, LEP, IL-6, and STAT3 and influencing the JAK2-STAT3 pathway." (PMID 35529938, 2022). "In lean individuals, adipocytes secrete anti-inflammatory mediators, such as IL-10 and adiponectin, whereas obesity leads to a proinflammatory signature featuring the release of TNF-α and IL-6, which can directly modulate ILC function." (PMID 35962192, 2022). "With the lipid accumulation in adipose tissues during obesity, fat macrophages release inflammatory cytokines, such as TNF-α and IL-6." (PMID 36157449, 2022). "The inflammatory factors, represented by interleukin-1β (IL-1β), interleukin-6 (IL-6) and tumor necrosis factor-α (TNF-α), are ultimately responsible for the inflammation in inflammatory bowel disease (IBD), obesity and other inflammation-related diseases." (PMID 35954128, 2022). "DCT prevented the obesity-induce upregulation of MCP-1 (p < 0.001) and IL-6 (p < 0.01) and DCTE also reduced the gene expression of TNF-α (p < 0.05)." (PMID 36139877, 2022). "After an obesity-induced IR model in mice was constructed, both TGF-β1 and IL-10 protein expressions were downregulated but those of IL-17 and IL-6 were upregulated (P < 0.001)." (PMID 33781239, 2021). "In metabolic disorders, such as obesity and T2D, coronary endothelial cell function is markedly impaired by high levels of circulating inflammatory mediators (e.g., TNF-α, IL-1β, and IL-6) contributing to insulin resistance." (PMID 34671656, 2021). "On the contrary, the mean concentration values for the inflammatory markers IL‐6, IL‐8, and TNF‐α were slightly higher in underweight/normal weight participants than in those with overweight/obesity." (PMID 33680494, 2021). "As an inflammatory state characterizes obesity and IR, we evaluated the gene expression of cyclooxygenase-2 (COX-2), TNF-α, IL-6, nuclear factor kappa B (NF-κB) and inhibitor of kappa B (IκB) by RT-qPCR in the liver." (PMID 34572325, 2021). "Notably, IL-6 regulation in adipocytes in obesity setting remains unclear." (PMID 34831450, 2021). "High level of IL-6 is also another key signature of severe SARS-CoV, MERS-CoV, and pandemic H1N1 influenza A viral infections In individuals with obesity, adipocytes secrete pleiotropic leptin and pleiotropic adipocyte-specific IL-6 cytokine." (PMID 34220807, 2021). "Obesity and MetSyn are characterized by low-grade inflammation and elevated pro-inflammatory cytokines, such as TNF-α, IL-6, and PAI-1." (PMID 34239993, 2021). "Type I interferon signaling, interleukin-6 (IL-6), and STAT3 signaling are required for healthy adipose tissue development and can be even protective against obesity-induced metabolic deterioration." (PMID 34571937, 2021).